NOTCH2NLA (notch 2 N-terminal like A)
Description:
Human-specific protein that promotes neural progenitor proliferation and evolutionary expansion of the brain neocortex by regulating the Notch signaling pathway. Able to promote neural progenitor self-renewal, possibly by down-regulating neuronal differentiation genes, thereby delaying the differentiation of neuronal progenitors and leading to an overall final increase in neuronal production. Acts by enhancing the Notch signaling pathway via two different mechanisms that probably work in parallel to reach the same effect. Enhances Notch signaling pathway in a non-cell-autonomous manner via direct interaction with NOTCH2. Also promotes Notch signaling pathway in a cell-autonomous manner through inhibition of cis DLL1-NOTCH2 interactions, which promotes neuronal differentiation (By similarity).
Synonyms: N2N; NOTCH2NL
Tractability: Antibody: UniProt places it where antibodies can reach, with high confidence; its Gene Ontology location is reachable by antibodies, with high confidence.
Gene: Protein-coding gene on chromosome 1 (146,145,929 to 146,229,073, reverse strand). Ensembl gene ENSG00000264343.
Subcellular location: Secreted; Cytoplasm
Pathways (Reactome):
Signal Transduction: Expression of NOTCH2NL genes; NOTCH2 Activation and Transmission of Signal to the Nucleus
Gene Ontology:
Molecular function: Notch binding; protein binding; calcium ion binding
Biological process: cerebral cortex development; positive regulation of Notch signaling pathway
Cellular component: cytoplasm; extracellular region
Homologues: Orthologues: Drosophila melanogaster N (43% identical), Caenorhabditis elegans lin-12 (8% identical), zebrafish notchl (1% identical). Paralogues in human: NOTCH2NLC (100% identical), NOTCH2NLB (99% identical), NOTCH2 (93% identical), NOTCH2NLR (90% identical), NOTCH1 (45% identical), NOTCH3 (38% identical), SNED1 (12% identical).
Diseases named in the same sentence as NOTCH2NLA in open-access papers:
NOTCH2NLA is named in the same sentence as 12 diseases in open-access papers, as found by Europe PMC text mining. Sharing a sentence is not in itself a finding about the gene and the disease. The quoted sentences say what the papers report.
microcephaly (4 papers, 2020 to 2023). A congenital or acquired developmental disorder in which the circumference of the head is smaller than normal for the person's age and sex. "Moreover, as two other human-specific genes are directly adjacent to NOTCH2NLA and NOTCH2NLB—that is, NBPF10 and NBPF14, respectively—mutations affecting these genes could be potentially important contributors to microcephaly." (PMID 34063381, 2021).
infection (1 paper, 2025). The state of being infected such as from the introduction of a foreign agent such as serum, vaccine, antigenic substance or organism. "Besides MUC19, there are other interesting CNVs shown from our primary infection model, including IRF4/DUSP22 duplication and Notch homolog 2 N-terminal-like protein A (NOTCH2NLA) deletion." (PMID 40996224, 2025).
NOTCH2NLA also shares sentences with these, for which no sentence is quoted: cancer (3 papers); metastatic cancer (2); tumor (2); autism (1); gastric cancer (1); genetic disorder (1); leukemia (1); neurodevelopmental disorder (1); neurological disorders (1); plasma cell neoplasm (1).